LEPR (leptin receptor)
Diseases named in the same sentence as LEPR in open-access papers (continued):
Sharing a sentence is not in itself a finding about the gene and the disease.
breast cancer (continued). "Many studies have been performed to investigate the correlation of leptin (LEP) and leptin receptor (LEPR) polymorphisms with breast cancer (BC) risk, however the results are inconclusive." (PMID 28938640, 2017). "This study aimed at investigating -2548 G/A polymorphism in leptin gene and Q223R polymorphism in leptin receptor gene in patients with breast cancer." (PMID 26199932, 2015). "Recent studies have shown that polymorphisms in leptin and leptin receptor genes are associated with increased risk for breast cancer." (PMID 26199932, 2015). "A number of studies support the association between high LEPR/leptin expression and breast cancer progression, metastasis and ER-negativity." (PMID 25482303, 2014). "This evidence is also confirmed by analysis of 33 patients with breast cancer at different stages of disease, demonstrating a significant association between the expression of leptin receptor and ERα." (PMID 25505738, 2014). "For example, LEPR Q223R was found associated with an increased risk for oral squamous cell carcinoma, breast cancer and non-small cell lung cancer." (PMID 23593308, 2013). "In contrast to another meta-analysis, however, we were not able to find a statistically significant association between LEPR Q223R and risk of breast cancer." (PMID 24146750, 2013). "Some investigators have examined the relationship between variants of the LEPR Gln223Arg polymorphism and serum levels of leptin since there is some evidence associating serum leptin levels with breast cancer risk." (PMID 19017403, 2008). "The homozygous LEPR Arg223Arg genotype was also associated with some modest increase in breast cancer risk (OR = 1.8, 95% CI 0.9–3.6, p = 0.12)." (PMID 19017403, 2008). "An important observation is the paucity of epidemiological literature on the role of polymorphisms in the leptin receptor (LEPR) gene in breast cancer susceptibility in most populations and its complete absence in sub-Saharan African populations." (PMID 19017403, 2008). "The heterozygous LEPR Gln223Arg genotype was associated with a modestly increased risk of breast cancer (OR = 1.8, 95% CI 1.0–3.5, p = 0.06)." (PMID 19017403, 2008). "Our results suggest that the LEPR Gln223Arg polymorphism in the extracellular domain of the LEPR receptor gene is associated with a modestly increased risk of premenopausal breast cancer in Nigerian women." (PMID 19017403, 2008). "In conclusion, this study has demonstrated a modestly increased risk of premenopausal breast cancer in women harboring the LEPR 223Arg allele of the LEPR Gln223Arg polymorphism of the leptin receptor gene." (PMID 19017403, 2008). "Among premenopausal women, there was a marginally increased risk of breast cancer with the LEPR 223Arg allele (LEPR Gln223Arg + LEPR Arg223Arg): OR = 1.8, 95% CI 1.0–3.3, p = 0.05." (PMID 19017403, 2008). "Despite these premises, very few studies have considered the role of serum leptin levels and polymorphisms in leptin and LEPR genes in breast cancer risk." (PMID 19017403, 2008). "Both leptin and leptin receptor have recently been implicated in processes leading to breast cancer initiation and progression in animal models and humans." (PMID 19017403, 2008). "There was no apparent difference in the distribution of the LEPR 223Gln and LEPR 223Arg alleles in postmenopausal women with breast cancer compared to the control subjects." (PMID 19017403, 2008). "Genotype frequencies of LEP and LEPR polymorphisms in relation to pathological indices of breast cancer severity." (PMID 16504019, 2006). "The breast carcinoma specific OVS was significantly shorter in the group of patients carrying LEPR 223R allele." (PMID 16504019, 2006). "Comparison of genotype frequencies of the LEPR Q223R alleles in patients with breast carcinoma and control subjects indicated an increase of LEPR 223QR and RR genotypes." (PMID 16504019, 2006).
breast cancer (continued). "Under dominant mode, the protective effects of LEP gene rs7799039 GG plus GA genotypes and LEPR gene rs1137100 AA plus AG genotypes on breast cancer risk dwindled, and the risk conferred by ADIPOQ gene rs1501299 TT plus TG genotypes was enhanced, with OR of 1.41 (95% CI: 1.06 to 1.88)." (PMID 37274250, 2023). "In addition, studies also showed that variants of LEP and LEPR gene are associated with breast cancer susceptibility." (PMID 35223490, 2022). "Among the 7 SNPs, LEPR rs1137101 showed a significantly decreased breast cancer risk under the dominant genetic model (GA + AA vs. GG, adjusted OR = 0.722, 95% CI = 0.584–0.893, p = 0.003) and co-dominant genetic model (GA vs. GG, adjusted OR = 0.719, 95% CI = 0.578–0.894, p = 0.003)." (PMID 35223490, 2022). "For LEPR rs4655555, a significant association with decreased ER+/PR+ breast cancer risk in the co-dominant genetic model (TT vs. AA, adjusted OR = 0.533, 95% CI = 0.321–0.884, p = 0.015) and the recessive model (TT vs. TA + AA, adjusted OR = 0.562, 95% CI = 0.341–0.925, P = 0.023) was identified." (PMID 35223490, 2022). "Rs1137101 was observed to influence the weight of the mother and the newborn in a Romanian study; likewise, the association between this genetic LEPR variant and a resistance to treatment against breast cancer in a population of overweight Mexican women was also reported." (PMID 35741707, 2022). "In human breast cancer, elevated LEPR expression is also associated with poor prognosis." (PMID 36077676, 2022). "For LEPR rs4655555, a significant association with decreased breast cancer risk was also identified in the co-dominant genetic model (TT vs. AA, adjusted OR = 0.574, 95% CI = 0.377–0.873, p = 0.009) and recessive model (TT vs. TA + AA, adjusted OR = 0.595, 95% CI = 0.394–0.899, p = 0.014)." (PMID 35223490, 2022). "The association of LEP/LEPR genetic variations with risk of ER+/PR+ and ER-/PR- breast cancer." (PMID 35223490, 2022). "Leptin levels, both in circulating plasma or expression in breast cancer tissue, are reported to have association with breast cancer progression Leptin and leptin receptor are overexpressed in breast cancer tissue probably due to hypoxia, IGF, estradiol, and insulin overexposure." (PMID 33482868, 2021). "Thus, we performed a systematic review and updated meta-analysis to obtain a more precise assessment of the association between PON1, LEP and LEPR polymorphisms and the risk of breast cancer." (PMID 34452542, 2021). "Moreover, the occurrence of LEPR gene polymorphisms (LEPR Gln>Arg) correlated with HER2 receptor expression in breast cancer cells of women from Greater Poland." (PMID 33864589, 2021). "Over the past decade, several molecular epidemiological studies have been performed to identify the association of PON1 rs662, rs854560, LEP rs7799039G>A, and LEPR rs1137101 polymorphisms with susceptibility to breast cancer, but the findings have been conflicting." (PMID 34452542, 2021). "Furthermore, in primary breast cancer, Jak2 mRNA has a positive association with both LepR (R = 0.61) and FGFR1 mRNA (R = 0.49)." (PMID 33019728, 2020). "Despite these limitations, our findings support the hypothesis that IHC expression of the adipokines and adipokine receptors, particularly LEPR, is associated with tumor features that are indicative of more aggressive breast cancer phenotypes." (PMID 32046756, 2020). "Here, we investigated the expression and the intracellular distribution of KH RNA binding domain containing, signal transduction associated 1 (KHDRBS1), leptin, leptin receptor (LEPR), and adiponectin in bone metastasis from breast carcinoma and looked for correlations between the data." (PMID 33213024, 2020). "Moreover, post-menopausal and pre-menopausal Mexican women appeared susceptible to develop breast cancer if the LEPR Q223R or the LEP G2548A polymorphisms, respectively, were present." (PMID 30404206, 2018).
breast cancer (continued). "In this latter case, it has been well demonstrated how cancer-associated fibroblasts express leptin receptor and secrete leptin, which sustains a short autocrine loop and is able to target tumor epithelial cells enhancing breast cancer cell motility and invasiveness." (PMID 25505738, 2014). "Liu and coworkers suggested that the LEPR Q223R polymorphism might be implicated in the development of breast cancer in East Asians and PON1 L55M might increase breast cancer risk." (PMID 23826274, 2013). "Furthermore, there have been some meta-analyses and systematic reviews that investigated the association between leptin receptor gene polymorphism and breast cancer." (PMID 23826274, 2013). "He’s group also suggested that LEPR Gln223Arg might be a low-penetrant risk for developing breast cancer, especially for black African women." (PMID 23826274, 2013). "Furthermore, overexpression of the leptin receptor is found in breast tumors with a high grade, a feature associated with TN breast cancer." (PMID 23181105, 2012). "The effect of genotypes such as LEPR Gln223Arg polymorphism on breast cancer may vary from one population to the other as a result of marked differences in the distribution of the alleles in different populations." (PMID 19017403, 2008). "Although, several polymorphisms have been described in the LEPR gene, we have chosen in this exploratory study to evaluate the role of the LEPR Gln223Arg polymorphism in breast cancer susceptibility in Nigerian women since it is the most studied functional LEPR gene polymorphism in human subjects." (PMID 19017403, 2008). "Our results indicated that the polymorphisms in LEP and LEPR genes are associated with increased breast cancer risk as well as disease progress, supporting our hypothesis for leptin involvement in cancer pathogenesis." (PMID 16504019, 2006). "We hypothesize that these leptin and leptin receptor polymorphisms associated with higher leptin serum levels and overexpression of leptin in adipocytes, favour breast cancer development and aggressiveness." (PMID 16504019, 2006). "In conclusion, this study suggests that genetic variation in the tandem LEP and its receptor LEPR may be attractive susceptibility markers for breast carcinoma." (PMID 16504019, 2006). "We have investigated whether genetic variations in LEP and LEPR have implications for susceptibility to and prognosis in breast carcinoma." (PMID 16504019, 2006). "Moreover, the presence of the LEP (-2548) A allele showed a significant association with decreased disease-free survival in breast carcinoma patients, and the presence of the LEPR 223R allele showed a significant association with decreased overall survival." (PMID 16504019, 2006). "In these dysfunctional ORGs, combined with relevant researches, ABCG1 is a potential target for treating ovarian cancer associated with ECM1-activated signaling, while LEPR is the one of breast cancer risk factors, indicating ORGs might play important roles in PRAD." (PMID 37788005, 2023). "Moreover, the encoding product of LEPR named the leptin receptor together with leptin maintains energy homeostasis and neuroendocrine function and has been correlated with the occurrence and development of gastric, colorectal, and breast cancer." (PMID 36052737, 2022). "Our study demonstrated that the polymorphisms rs1137101 and rs4655555 located in the LEPR gene decreased breast cancer risk in Chinese females, which might be a research-worthy bio-diagnostic marker and applied for early prediction and risk assessment of breast cancer." (PMID 35223490, 2022). "We further identified that a high expression of LEPR significantly correlated with worse prognosis of breast cancer patients, which suggesting that the rs4655555 variant may affect breast cancer risk and development through regulating the expression of LEPR, and subsequently prognosis." (PMID 35223490, 2022).
breast cancer (continued). "Finally, we studied whether body weight is associated with the expression of leptin receptor (Ob-R) in the mammary tumor microenvironment of mice with different weights." (PMID 25599228, 2015). "The results showed that leptin, leptin/BMI ratio, FLI and visfatin were significantly higher and soluble leptin receptor ObRe was significantly lower in patients with breast cancer." (PMID 40902078, 2025). "Despite these promising results, ongoing challenges limit the use of LEPR antagonists to inhibit angiogenesis in breast cancer patients." (PMID 39439572, 2024). "For example, in a model of 4T1 mammary carcinoma cells grown adjacent to the mammary fat pad of syngeneic mice, leptin receptor antagonists reduced tumor growth by up to 90% and this was associated with reduced VEGF and VEGFR tumor expression." (PMID 39439572, 2024). "Both LEP and LEPR showed high expression in breast cancer tissues and low expression in benign breast tissues." (PMID 36941557, 2023). "The leptin receptor and ER-α are co-expressed in breast cancer tissue and engage in functional crosstalk with the IGF-1R and transactivation of EGFR." (PMID 37233716, 2023). "The results showed that mammospheres (aggregates of mammary epithelial stem cells) were significantly less likely to form in breast cancer cell lines and the patient-derived samples when leptin signaling was inhibited by a full leptin receptor antagonist." (PMID 38202341, 2023). "This is thought to be due to increased expression of the membrane leptin receptor (ObRl/Rb) in ER+ breast cancer cells and its co-localization with the ER-α, together with leptin effects on breast cancer stromal aromatase activity." (PMID 37233716, 2023). "The co-expression of LEP and LEPR in primary BC showed that LEP expressed on mammary tumor cells via an autocrine pathway." (PMID 36941557, 2023). "Recently, in mammary tissues of a rat model of breast cancer driven by diet-induced obesity, increased expression of the leptin/leptin receptor (Ob/ObR) along with signaling activation were found." (PMID 37509120, 2023). "Previous studies indicated that leptin signaling played a key role in breast cancer incidence and development, and a higher expression of leptin and LEPR was also validated in breast cancer tissues." (PMID 35223490, 2022). "The association between LEPR or LEPROT level and outcomes of breast cancer patients was further evaluated by Kaplan–Meier survival analysis based on TCGA-BRCA data." (PMID 35223490, 2022). "In breast cancer leptin and LEPR expression is higher in tumor cells than in the normal breast epithelial cells and associated with tumor size and high tumor cell proliferation." (PMID 36077676, 2022). "Park and colleagues demonstrated that leptin receptor signaling affects breast cancer cell metabolism by suppressing mitochondrial respiration in animal models, and enhancing the classically described Warburg’s effect." (PMID 36361728, 2022). "Expression of leptin and its receptor in breast cancer samples correlates with tumor aggressiveness, and leptin/leptin receptor signaling activation is involved in breast cancer progression and metastasis." (PMID 36361728, 2022). "These discoveries open exciting opportunities for future investigations on how glutamine metabolism in the endothelium affects leptin and leptin receptor in breast cancer." (PMID 36381236, 2022). "In the current study, we recruited 1,616 participants including 963 breast cancer cases and 953 cancer-free controls to assess the correlation between LEP/LEPR polymorphisms and susceptibility of breast cancer." (PMID 35223490, 2022). "Leptin (LEP) plays a physiological role through its specific receptor (LEPR) and is involved in the occurrence and development of breast cancer." (PMID 35223490, 2022). "It has been previously shown that expression of LEPR in breast cancer cells is responsible for maintaining CSC-like and metastatic properties." (PMID 36077676, 2022).
breast cancer (continued). "The first leptin peptide analogues with antagonistic activity towards leptin receptor and efficient anti-tumor activity in breast cancer were designed based on leptin binding sites II and I." (PMID 34356668, 2021). "SNPs of the LEPR gene have been investigated in various local populations and differentdiseases like breast cancer, non-small-cell lung cancer, oral squamous cell carcinoma,diabetic macroangiopathy and essential hypertension." (PMID 33687165, 2021). "The use of leptin receptor antagonists has been extensively studied for the treatment of breast cancer." (PMID 34356668, 2021). "LDFI peptide significantly reduced exosome secretion in both MCF-7 and MDA-MB-231 breast cancer cells, demonstrating the leptin/leptin receptor/Hsp90 axis as an important regulator of exosome generation in mammary carcinoma cells." (PMID 34356668, 2021). "In breast cancer, leptin and the leptin receptor are overexpressed in primary and metastatic lesions compared to non-cancer tissues." (PMID 33987528, 2021). "In both ER+ and ER− breast cancers, there was a positive association between FGFR1 mRNA, and LepR mRNA, although ER- tumors had significantly higher leptin mRNA compared to ER+ tumors." (PMID 33019728, 2020). "In human breast cancer cells, Sam68 participates in leptin receptor signalling by modulating the trophic effects of the hormone in cellular proliferation and growth." (PMID 32033341, 2020). "Consistently, the positive correlation between PAI-1 and LEPR was validated in clinical breast cancer specimens." (PMID 33371368, 2020). "KHDRBS1 is also involved in the signalling pathway of leptin receptor (LEPR) in breast cancer cells as a transducer that mediates the effects of the hormone on cell proliferation and growth." (PMID 33213024, 2020). "Here, we examined leptin receptor expression and bone metastasis in tissue samples from 96 breast cancer patients." (PMID 32836215, 2020). "Leptin receptor expression was higher in metastatic tissues than in the original breast cancer tissues." (PMID 32836215, 2020). "One report demonstrated that a high expression of LepR in breast cancer tissue predicts poorer outcomes in patients with high, but not low, sera leptin." (PMID 33019728, 2020). "Next, we examined expression of the leptin receptor in breast cancer-derived bone metastatic tissues." (PMID 32836215, 2020). "Taken together, these results indicate that the leptin receptor promotes bone metastasis in breast cancer patients." (PMID 32836215, 2020). "Breast cancer patients are characterized by high serum leptin concentrations as well as increased leptin receptor expression especially in higher pathological grade tumor tissues and patients who develop resistance to anti-cancer treatments." (PMID 32257945, 2020). "Bone metastases from breast cancer express components of the leptin/LEPR/KHDRBS1 axis in an expression pattern that partly follows that of the primary tumour but also exhibits peculiarities." (PMID 33213024, 2020). "First, we examined leptin receptor expression in 96 breast cancer tissues using IHC staining and identified correlations between leptin receptor expression and clinicopathologic features." (PMID 32836215, 2020). "Both FGFR1 and LepR, independently, have been shown to increase breast tumor size and lead to a reduced overall survival in breast cancer patients." (PMID 33019728, 2020). "With the present study, we investigated the expression and the intracellular distribution of KHDRBS1, leptin, and LEPR in bone metastasis from breast carcinoma and looked for eventual correlations between them." (PMID 33213024, 2020). "Leptin, by binding to the leptin receptor (OB-R), promotes breast cancer cells to proliferate and develop." (PMID 31500658, 2019). "Different proposed therapeutic strategies for breast cancer treatment include the use of soluble leptin receptors, peptide-based leptin antagonists and leptin receptor blocking antibodies." (PMID 31380268, 2019).